KRAS (KRas proto-oncogene, GTPase)
Diseases named in the same sentence as KRAS in open-access papers (continued):
Sharing a sentence is not in itself a finding about the gene and the disease.
tumor (continued). "In fact, RCC2 was found to be an independent prognostic biomarker in multivariable analysis of chemotherapy-untreated stage I–III patients, after adjusting for TNM stage, patient age, sex, tumour location, MSI status, CDX2 expression, BRAFV600E- and KRAS mutation status." (PMID 33219056, 2020). "Combined, our chemical inhibitor screening, gene knockdown and bioinformatic analyses consistently indicate a collaborative role of the integrin-FAK pathway and BRD4/Myc-linked epigenetic network in controlling tumor cell variability in NSCLC, regardless state of KRAS or EGFR." (PMID 32793596, 2020). "Using the G12D KRAS mutations as neoantigens, we found that vaccination of mice with naked synthetic peptides harboring the G12D mutation with CpG adjuvant stimulated mainly CD4+ T cell responses with limited tumor growth inhibition." (PMID 33298945, 2020). "We used the murine CRC cell line CT26, which harbors a homozygous KRAS mutation at G12D and shares with aggressive, undifferentiated, and refractory human CRC cells, and thus contains highly severe tumor model features for the evaluation of the effectiveness of FTD/TPI." (PMID 33333866, 2020). "Overexpression of TWIST1 is reported to override Myc-induced apoptosis in tumor cells and along with the other changes, could be a compensatory response by the Pa16C KRAS-mutant pancreatic cells to survive KRAS suppression." (PMID 32576853, 2020). "In agreement with the selective toxicity of STS + vitamin C in KRAS-mutant tumor cells, we found that HT29 and SW48 cells genetically modified to express the active form of KRAS were more susceptible to STS + vitamin C compared with their wild-type isogenic counterpart." (PMID 32393788, 2020). "We posit that these changes in the mechanical responsiveness of malignant cells by oncogenic KRas could distort the sensing of physical signals in the tumor microenvironment." (PMID 33020304, 2020). "Moreover, oncogenic KRAS expression has specifically been shown to induce aberrant DNA methylation, promoting hypomethylation across the genome while silencing key tumor suppressors through hypermethylation." (PMID 32576853, 2020). "KRAS activity regulates tumor progression, differentiation, metastasis and survival." (PMID 33060649, 2020). "In tumors with mutations of KRAS, NRAS, PIK3CA, or BRAF, the proportion of VAF with different mutations in tumor cell samples of the same patient varies significantly, which may also reflect the ITH of tumor cells." (PMID 32853464, 2020). "Here, we show for the first time that PTPN2 plays a tumor-promoting function in KRAS-driven cancer." (PMID 33122197, 2020). "Additional genetic alterations can co-exist with a primary targetable oncogenic “driver” alteration (e.g., oncogenic EGFR, ALK, KRAS) and may help promote tumor progression and limit therapy response." (PMID 32822576, 2020). "The best compound 3144 was tested against a number of different cell lines with WT and mutant NRAS (G13D, G13V), and selective inhibition was observed against mutant NRAS cells; moreover, it was able to decrease tumour growth in MDA-MB-231 (KRAS-G13D) and PDTALL22 (NRAS-G13V) xenograft mouse models." (PMID 32770300, 2020). "In addition, KRAS mutations were shown to upregulate GM-CSF in TME of pancreatic and CRCs, which enhances the infiltration of MDSCs causing an evasion of anti-tumour immunity." (PMID 33116132, 2020). "Given the relatively high prevalence of KRAS mutations in the Iranian CRC patients, these findings alert physicians to patients that may be at elevated risk for carrying a tumor with KRAS mutation as the focus for screening." (PMID 33680376, 2020).
tumor (continued). "Finally, comparing tumor DNA results, 24 patients with BRAF, KRAS and NRAS mutations had shorter survival than 33 patients without these mutations (25 months vs. 61months, P=0.0334)." (PMID 32284750, 2020). "In the discovery cohort, patients expressing mutant KRAS or RAS exhibited no significant SNP-associated differences in tumor progression or survival outcomes." (PMID 32629861, 2020). "The tumor characteristics of metabolic subtypes of CRC, such as consensus molecular subtype 3 or KRAS mutations, may also be related to MVA pathway activation." (PMID 32911743, 2020). "It has become more evident that oncogenic KRAS mutations mediate autocrine effects and crosstalk with the TME, particularly by promoting inflammation and evading the immune response and ultimately leading to tumour progression, invasion and progression." (PMID 33116132, 2020). "Moreover, our results provide evidence suggesting that the main contributor of the miR181 family to the tumor phenotype induced by mutant KRAS is miR181ab1, similarly to what have been reported previously in a GEMM of Notch-induced T-ALL." (PMID 31874105, 2020). "The difference in KRAS mutations by tumor location for this stratification was no longer statistically significant in these analyses." (PMID 31856410, 2020). "However, the precise mechanisms by which oncogenic KRAS induces immunosuppressive tumor microenvironment remain elusive." (PMID 33194642, 2020). "A liquid biopsy can be used to detect KRAS mutations in cfDNA in the absence of detection from a primary tumor biopsy." (PMID 32471160, 2020). "In addition, we have found an association between KRAS or BRAF mutation status and the differentiation grade of tumors, which suggests a role of these activating mutations in tumor development and progression." (PMID 31952366, 2020). "KRAS positivity was confirmed in one available matched tumor tissue biopsy at diagnosis." (PMID 33520716, 2020). "As RAS proteins are highly immunogenic, another potential therapeutic approach might be the adoptive transfer of genetically engineered tumor antigen-specific T cells into patients with KRAS-mutant tumors." (PMID 32548736, 2020). "Moreover, there was a significant association between a KRAS MAF >1% in exosomal DNA and tumor progression on radiographic images." (PMID 33297544, 2020). "Our data show that PTPN2 plays an important role in the maintenance of KRAS-dependent tumor cells." (PMID 33122197, 2020). "As an alternative, recently developed methods for so-called liquid biopsy analyzing circulating tumor DNA (ctDNA) from peripheral blood can provide a rapid KRAS genotyping that is relatively non-invasive and with a minimal risk of complications compared to tissue biopsy." (PMID 32867151, 2020). "In patient 23, an additional KRAS Q61H mutation was found in cfDNA from bile but not in FFPE-tumor DNA." (PMID 33375555, 2020). "The abundance of miR-34 suppresses KRAS thus preventing tumour formation and progression." (PMID 32577155, 2020). "There are several potential mechanisms by which KRAS mutant cancer cells may suppress the anti-tumor T cell response." (PMID 33194642, 2020). "BRAF and KRAS mutations could lead to the abnormal activation of Ras-Raf-MEK-ERK pathway, thus promoting the growth and proliferation of tumor cells." (PMID 33088218, 2020).
tumor (continued). "While oncogenic KRAS and phosphatidylinositol 3-kinase (PI3K) cause divergent metabolic phenotypes individually, how they synergize to promote tumor metabolic alterations and dependencies remains unknown." (PMID 32101748, 2020). "The resulting peptides were able to bind to wild type and all mutant forms of KRAS with high affinity (nanomolar range) and displayed similar antitumoral activity in vitro in both KRAS wild type and in mutant cell lines, thus generating concerns about the tumor selectivity of the peptides." (PMID 31636382, 2020). "The MAF of serum KRAS showed recurrent tumor tissue KRASG12/13 wild type (B4) showed 0.32% MAF." (PMID 33585224, 2020). "Targeting the KRAS effector signaling pathways could also prove efficacious in treating tumors with KRAS mutations, as the inhibitors have entered clinical trials demonstrating promising clinical activity in KRAS mutant tumor." (PMID 33122197, 2020). "Based on our results, we propose that B3GNT3 overexpression, SMAD4 inactivation, and KRAS activation may interact to promote tumor growth and inhibit the infiltration of CD8+ T cells in PC." (PMID 33316775, 2020). "Moreover, it was also reported in that wild-type KRAS has a tumour-suppressor effect in some KRAS-mutant cancers." (PMID 32770300, 2020). "Tumour tissue was analysed for MSI (microsatellite instability), CIMP (CpG island methylator phenotype), BRAF (B-Raf proto-oncogene serine/threonine kinase gene) and KRAS (Kirsten rat sarcoma viral oncogene homologue gene) mutations." (PMID 32225169, 2020). "Both KRAS and PTPN2 knockdown could dramatically decrease the phosphorylation levels of MEK and ERK in KRAS-dependent tumor cell lines HCT-116, PaTu8988T, and H460." (PMID 33122197, 2020). "In addition, in an NSCLC patient‐derived xenograft with KRAS G12C mutation, ARS‐1620 showed tumor regression, and effectively inhibited the downstream ERK phosphorylation and activated apoptosis." (PMID 33022831, 2020). "We assessed a homogenous KRAS mutation status between several pre- and post-therapeutic tissue samples of the primary tumor indicating no relevant intratumoral heterogeneity and concluded, that discordance is a very rare event." (PMID 33002027, 2020). "Mut-KRAS in tumor tissue was initially analyzed by NGS and then by ddPCR." (PMID 33322500, 2020). "As this pathway is central for the tumor behavior, often associated with oncogene addiction, for diagnostics and therapy design, in this work, all NSCLC analyses were performed under consideration of the EGFR/KRAS mutational background." (PMID 32605217, 2020). "Additionally, 54 patients (56.25%) were negatively concordant; that is, both plasma cfDNA samples and tumor DNA were KRAS G12/G13 wild-type." (PMID 33233668, 2020). "These immune-cold CRCs were associated with tumour hypoxia, confirmed using CAIX immunohistochemistry (P = 0.0009), which may mediate disease progression through common biology (KRAS mutations, CRIS-B subtype and SPP1 mRNA overexpression)." (PMID 32684627, 2020). "All patients with positive KRAS or BRAF-mutated ctDNA presented the same mutation in their tumor with no false positive cases." (PMID 32517177, 2020). "In 48.6% (N = 17/35 cases) of patients with KRAS mutations in tumor tissues, no mutations were detected in cfDNA." (PMID 33233668, 2020). "The observations of less than 5% VAF of the IDH1 mutation in cases 3, 5, and 6 in a contexts of 51%‐70%, 31%‐50%, and 41%‐60% estimated tumor cellularity and 33%, 13%, and 18% VAF of the coexisting EGFR, KRAS, or PIK3CA mutation suggest presence of IDH1 mutation in a tumor subpopulation." (PMID 32333643, 2020).
tumor (continued). "ctDNA analysis of pre- and post-operative plasma samples and tumor tissue (n = 42) using PCR-based SafeSeqS assays to identify KRAS mutation (codons 12, 13, and 61) identified RAS mutations in 90.5% of tumor samples and in 62.2% of 37 pre-operative and 37.1% of 35 post-operative plasma samples." (PMID 32010431, 2020). "Using 1010 matched case-control pairs within the NSHDS, we investigated circulating levels of insulin, C-peptide, adiponectin, and leptin in relation to the risk of CRC, and molecular subtypes of CRC defined by KRAS and BRAF mutation status and MSI status in the tumor." (PMID 32210264, 2020). "The ability of the FMD to prevent vitamin C-induced HO-1 upregulation in KRAS-mutant cancer cells prompted us to investigate whether HO-1 levels affect the sensitivity of tumor cells to the combination treatment." (PMID 32393788, 2020). "Tumor wild-type KRAS status seems to be a contributory factor in the ICD generation." (PMID 31893287, 2020). "Alternatively, targeting activated KRAS with overexpression of tumor suppressors miR-193a-3p and miR-181a-5p could potentially inhibit further progression of tumor growth." (PMID 32316322, 2020). "While the pan-RAS degrader significantly impeded H1299 tumours burden, the KRAS degrader caused almost no inhibition." (PMID 32591521, 2020). "Patients whose tumor is in the proximal colon are more likely to harbor mutations in KRAS or BRAF. t-SNE and Artificial Neural Network analyses showed systematic associations between tumor location, age, city of origin, histological subtype, and histological grade and KRAS mutational status." (PMID 32628708, 2020). "Therefore, new strategies are needed to specifically target the larger number of other tumours expressing mutant KRAS." (PMID 32591521, 2020). "KRAS mutant cancer cells suppress the anti-tumor T cell response." (PMID 33194642, 2020). "Furthermore, treatment with pharmacological PKC inhibitors impaired tumour growth and correlated with KRas dephosphorylation and subsequent apoptosis." (PMID 32456244, 2020). "The gain of more copies of mutant KRAS can transform the metabolic profile of lung cancer cells from a more glycolytic state to an enhanced Krebs cycle and glutathione-synthetic state, which enhances tumour-cell invasiveness." (PMID 31819196, 2020). "KRAS and HRAS mutations were detected in 35% (18/51) and 33% (17/51) of tumours, respectively." (PMID 31960612, 2020). "How different KRAS variants impact tumor initiation and progression in vivo has not been thoroughly examined." (PMID 33244099, 2020). "Therefore, molecules able to interfere with mutant KRAS protein are potentially important for wide-ranging tumour therapy." (PMID 32591521, 2020). "miR-139-5p was selected from the downregulated miRNAs in KRAS-mutant cells for further investigation because it has been reported to be a tumor suppressor in several cancer types 16, 17, 25, yet its relation to KRAS mutation remains unclear." (PMID 32641995, 2020). "Besides, STK11/LKB1 is one of the most commonly inactivated tumour suppressors in NSCLC, especially in those harbouring KRAS mutations." (PMID 33116132, 2020). "KRAS is an important oncogene and a key tumour maintenance gene in many carcinomas." (PMID 32944001, 2020). "In order to unravel the key differences between these two distinct responses, tumor cell‐specific RNA sequencing profiling revealed that KRAS signaling could be involved in this divergent invasive behavior upon antiangiogenic treatment." (PMID 33151035, 2020). "The KRAS mutation is near universal in PDAC, with 94% of tumours possessing the mutation." (PMID 32423157, 2020). "Indeed, the combination of STS and vitamin C selectively exacerbated ROS production in KRAS-mutant tumor cells." (PMID 32393788, 2020). "Altogether, the observations argue that wild-type KRAS status is a contributory and not a causative factor for tumor ICD." (PMID 31893287, 2020).
tumor (continued). "The fact that KRAS mutations in women are not affected by exposure to acrylamide remains a mystery to be elucidated by experiments that take into account tumor and environmental heterogeneity, especially hormonal differences between the two sexes." (PMID 32723394, 2020). "The finding that KEAP1 transcript levels are modulated by methylation only in KRAS wild-type NSCLC might indicate that methylation is a KRAS-independent mechanism to modulate NRF2 levels in tumor cells." (PMID 32971994, 2020). "In addition, functional validation of miRNAs involved in KRAS-driven oncogenesis has focused primarily on the role of such miRNAs in tumor initiation, with less attention on their role in tumor progression." (PMID 31874105, 2020). "In addition, our data highlighted the efficacy of our KRAS degrader in vivo, with a rapid regression of mutant KRAS tumours." (PMID 32591521, 2020). "Notably, mutations in NFE2L2, KEAP1 and CUL3 that cause persistent upregulation of NRF2 often co-exist with mutations that activate KRAS and the PI3K-PKB/Akt pathway, suggesting NRF2 supports growth of tumours in which KRAS or PKB/Akt are hyperactive." (PMID 33276631, 2020). "Mutant KRAS could up-regulate immunosuppressive cells in tumor such as myeloid-derived suppressor cells (MDSCs), CD4+FoxP3+ T regulatory cells, and CD19+IL10+ B regulatory cells." (PMID 32206449, 2020). "Therefore, our results demonstrate the reproducibility of KRAS testing in the primary biopsy as well as in the resected specimen within the same primary tumor as well as in the corresponding metastatic tissue." (PMID 33002027, 2020). "Furthermore, preclinical studies also suggest that BI 1701963 indeed blocks tumor growth both in G12 and G13 KRAS-mutant tumors, and the compound is selective for KRAS-mutant cell lines." (PMID 32548736, 2020). "While EMT and angiogenesis are typically involved in tumor progression, dysregulation of the hedgehog signaling, KRAS signaling, Wnt-β-catenin signaling, and UV response could drive colorectal tumorigenesis." (PMID 33336074, 2020). "We noted that KRAS was highly expressed in CRC tumour tissues and cell lines." (PMID 32944001, 2020). "Mitochondrial respiration differs in KRAS, BRAF mutated and wild-type tumor groups, confirming that oncogenes may affect the metabolic requirements of cancer cells." (PMID 32231083, 2020). "The role of KRAS in facilitating tumor metastasis depends on the effect of activated metalloproteases-7 and urokinase plasminogen activator, which breakdown and promote migration through the basement membrane, leading to the dissemination of cancer cells from the primary tumor." (PMID 32899322, 2020). "Within KRAS amplified tumors we revealed intratumoral heterogeneity that may define a (more aggressive) tumor cell population which is more frequently observed in patients with lymph node metastases." (PMID 32571252, 2020). "Study designs (mainly retrospective or posthoc analyses), tumor heterogeneity, primary tumor location, assessment of MMR, as well as adjuvant therapies received, could have influenced the prognostic value of KRAS mutations." (PMID 32707813, 2020). "Although the mechanistic basis for this relationship remains unknown, variation in tumor 24-hydroxylase levels may contribute to a differential benefit of vitamin D supplementation in patients with KRAS-mutant and EGFR-mutant tumors." (PMID 32183160, 2020). "Additionally, oncogenic KRAS also increases tumor PD-L1 expression and promotes CD8+ cells infiltration into the tumor stroma." (PMID 33194642, 2020).